SNORA20B (small nucleolar RNA, H/ACA box 20B)
Gene: Small nucleolar RNA gene on chromosome 7 (39,329,003 to 39,329,134, reverse strand). Ensembl gene ENSG00000206947.
Gene Ontology:
Biological process: RNA processing
Cellular component: nucleolus
Homologues: Orthologues: chimpanzee SNORA20B (98% identical), macaque SNORA20B (79% identical), mouse Gm24615 (70% identical). Paralogues in human: SNORA20 (92% identical).